TGFB1 (transforming growth factor beta 1)
Diseases named in the same sentence as TGFB1 in open-access papers (continued):
Sharing a sentence is not in itself a finding about the gene and the disease.
cancer (continued). "TCF4–TWIST1 interaction regulates TGFβ1 signalling-induced EMT and cancer metastasis." (PMID 35406121, 2022). "The functional role of EV-derived TGFB1 and ILK in cancer has been reported earlier." (PMID 36505879, 2022). "In addition to this, transforming growth factor beta 1 TGF-β1 and insulin-like growth factor 1 IGF-1, stored in the bone matrix and released upon cancer-induced bone resorption by osteoclasts, are responsible for TRPV1 expression and activity upregulation." (PMID 35163823, 2022). "Postnatally, TGFβ1 induces EMT in wound healing, fibrosis, and cancer." (PMID 35745656, 2022). "VEGF and TGFβ1 have shown positive correlation with cancer, and the expression of both are negative correlated with CAMK2B, suggesting they also act as downstream effectors of CAMK2B in KIRP." (PMID 35127542, 2022). "Recent single-cell transcriptomic studies have identified an inflammatory CAF (iCAF) subpopulation in several cancer types and described CAF plasticity, whereby cells in culture can be skewed between myoCAF and iCAF phenotypes by modulating TGFβ1 and IL1 signaling, respectively." (PMID 36353752, 2022). "In addition to TGFB1 and IL10, gene expression of IFNG, IL6, and CXCL8 were all significantly increased (p < 0.05) in mesenchymal samples for more than half of the cancer types." (PMID 35096592, 2021). "Furthermore, 17β-estradiol supplementation increased mRNAs for CXCL12, TGFβ1, and LTBP1, predicting heightened immunosuppression, metastasis, and cancer stem cell activity." (PMID 34359625, 2021). "Moreover, FUCA2 level showed a positive relationship with most immunosuppression genes, including programmed death-ligand 1 (PD-L1), transforming growth factor beta 1 (TGFB1), and interleukin-10 (IL10) in most cancer types." (PMID 34745134, 2021). "Further, our co-expression analysis also showed that key EMT-related factors such as MMP2, MMP9, CDH2, TGFB1, and VIM were highly expressed when CHN1 was highly expressed, while CDH1 was expressed at lower levels, suggestive of a potential cancer-promoting function of CHN1." (PMID 34152250, 2021). "Collectively, this study suggested that NSC765598 has a potential for multi-target inhibition of EGFR/iNOS/mTOR/TGFB1/FGFR/MAP2K1 and could serve as a lead compound for developing new therapeutics for cancer treatment." (PMID 33842373, 2021). "Notably, EGFR and its receptors, including TGFB1, MIF, HBEGF, GRN, COPA, and AREG, were upregulated in cancer cells and fibroblasts." (PMID 34326696, 2021). "TNF-α and TGFβ1 upregulate cyclooxygenase-1 (COX-1) and COX-2 expressions of mast cells and PG generation, which substantially affects skin carcinogenesis development by enhancing epidermal proliferation and stimulating inflammation within a cancer." (PMID 33917793, 2021). "To identify the role of cancer cells in TGFβ1 expression by hepatocytes, we examined the expression of TGFβ1 in IHH hepatocytes in the presence or absence of cancer cells (HCT116, HT29, LS174, LS180, SW620, and COLO320dm) using insert co-culturing approach." (PMID 34376784, 2021). "Cancer cells themselves induce the osteoclastic bone resorption by secreting factors, such as parathyroid hormone-related protein (PTHRP), which in turn secrete TGFβ1 that further induces PTHRP secretion." (PMID 34208521, 2021). "Therefore, we predicted VEGFA, APLN, and AGT genes as paracrine effectors for the cancer-stroma interaction in KIRCs, whereas DLL4, APP, and TGFB1 genes to be potential autocrine effectors." (PMID 35079698, 2021). "Myoferlin, a protein involved in plasma membrane function and repair, is overexpressed in several invasive cancer cell lines, and in MDA-MB-231 BC cells promoted EMT, migration and invasion by enhancing endogenous TGFB1 transcription and TGF-β1 protein secretion." (PMID 33478130, 2021). "The absence of RUNX1 in the co-cultured cancer cells resulted in lower expression of TGFβ1 in hepatocytes." (PMID 34376784, 2021).
cancer (continued). "Accordingly, any positive staining of adjacent cancer cells for TGFβ1 is most likely due to their uptake of the secreted TGFβ1 from the liver parenchyma (hepatocytes) rather than an upregulated expression of TGFβ1 in cancer cells." (PMID 34376784, 2021). "This is not surprising since carcinoma cells responding to signals such as inflammation, hypoxia and TGFβ1, upregulate a transcriptional program that triggers EMT and stemness also serve as drivers of CD73 expression." (PMID 33430239, 2021). "Given the roles of pHi and pHe in general, and NHE1 and NBCn1 in particular, in cancer cell motility and invasion, we asked whether NHE1 and NBCn1 impacted TGFβ-1-induced invasiveness." (PMID 32457840, 2020). "TAM secrete an excess of some pro-inflammatory (e.g., IL-6, TNF-α), several anti-inflammatory (e.g., IL-10, TGFβ1) and pro-angiogenic (e.g., VEGF, FGF-2) factors and TME remodeling matrix metalloproteinases (MMPs), which together promote cancer growth, survival and metastasis." (PMID 32899119, 2020). "In light of significance of TGFβ1, SHH, EGFR, and LEF‐1 in the proliferation and migration of cancer cells, we examined the differential expression of those proteins in the cell lysis solution of NFs and CAFs and paid our attention to the different expression of SHH." (PMID 32030915, 2020). "In both cancer types, the small GTPase RAC1B inhibits cell motility induced by recombinant human TGFβ1 via downregulation of the TGFβ type I receptor, ALK5, but whether RAC1B also impacts autocrine TGFβ signaling has not yet been studied." (PMID 33260366, 2020). "We assessed four different cancer cell lines capable of undergoing an EMT (A549, lung; DU145, prostate; MCF7, breast; and OVCA420, ovarian) and exposed each to known EMT-inducing factors: TGFB1, EGF, and TNF." (PMID 32358524, 2020). "TGFβ1 could activate SMAD2 and SMAD3 in cancer cell which form complexes with transcriptional coactivators or cosuppressors to regulate gene expression." (PMID 31753020, 2019). "In addition, the role of TGFβ1, a key player in driving EMT progress during cancer development, was further characterized in terms of its relationship with the cirrhotic ECM." (PMID 31905709, 2019). "TF WDR1 could positively regulate target gene TGFB1 to promote cancer cell proliferation, epithelial–mesenchymal transition (EMT), and migration, and to suppress cancer cell differentiation." (PMID 31126066, 2019). "Therefore, TGFβ1 contributes for NSCLC metastasis through promoting EMT, generation of high invasive cancer cells with stem-like properties, and increasing VEGF-C expression." (PMID 29995950, 2018). "To investigate whether TGFβ1 is capable of increasing NSCLC stem-like cell population, we measured mRNA expression level of cancer stem cell markers, including Oct4, Nanog, and Sox2, using real-time PCR." (PMID 29995950, 2018). "How TGFβ1 contributes to NSCLC metastasis and cancer stem-like cell generation is probably complex." (PMID 29995950, 2018). "Activation of the TGFβ1 signaling pathway, expression of EMT-ATFs (EMT activating transcription factors), or forced downregulation of E-cadherin resulted in increased metastasis in various cancer models." (PMID 30237490, 2018). "Besides TGFβ1/Smad2/3 cascade, there are also Smad-independent pathways involved into TGFβ1-induced EMT of cancer, such as MAPKs and Akt." (PMID 30174709, 2018). "At higher magnification, areas of intramucosal carcinoma without a lymphoid stroma showed inconspicuous signals for TGFβ1, contrasted by prominent signals in the lymphoid stroma." (PMID 29594353, 2018). "As TGFβ1 has been shown to induce FOXP3 expression in naïve T cells, we next determined whether our cancer cell lines expressed TGFβ1 by flow cytometry." (PMID 28239749, 2017). "The TGFβ1 signaling pathway activates transcription factors intimately involved in many normal and benign functions that, when commandeered by PDAC, permit the cancer to be refractory to standard therapy." (PMID 27895310, 2017).
cancer (continued). "Moreover, some of the platelet-derived biological factors (e.g., PDGF, TGFβ1, ATX) have been studied independently of platelets and showed an active role in cancer progression." (PMID 28737696, 2017). "This study, albeit in a different cancer indication, supports our findings and suggest that MDA-9 could act upstream of TGFβ1 to mediate cytoskeletal rearrangements." (PMID 27863394, 2016). "The products of several genes from our potential cell surface list are suspected of playing key roles in more general cancer-related activities such as immunosuppression/evasion (CD14 and CD86), cell migration (ICAM, CDH11) and proliferation (TGFB1, PMEPA1, PDGFRL, SLC19A3)." (PMID 27363029, 2016). "We should also mention the potential added value of the therapeutic targeting of integrins as a means of regulating TGFβ1 activity in cancer and fibrosis as opposed to directly targeting the TGFβ1 signalling pathway." (PMID 27515461, 2016). "Notably, treatment of neutralizing TGFβ1 or TGFβR1 inhibitor, SB431542 reversed CAF-CM induced cancer cell invasion and EMT." (PMID 26152796, 2015). "Here we found TGFβ1 signaling could also go through modulation EMT signaling and alternation the cancer stem-like cell population." (PMID 25483103, 2015). "LRG directly binds to transforming growth factor beta 1 (TGFβ1) and modulates TGFβ1 signaling in endothelial cells; however, the precise function of LRG in cancer remains unclear." (PMID 25826092, 2015). "Notably, miR-107 and TGFB1 are negatively correlated in both CRC and HNSC in our pan-cancer TCGA data compendium along with other cancer types." (PMID 25403569, 2014). "In addition, few studies have investigated the functional and clinical significance of TGFβ1 and HGF proteins, secreted by dysplasia epithelial cells, cancer cells and stroma fibroblasts, in oesophageal carcinogenesis." (PMID 24137336, 2013). "Recent reviews provide more detailed analysis of non-Smad signaling pathways and potential impact on cancer and potential targets for inhibition of TGFβ1 driven invasion and metastasis." (PMID 23326666, 2012). "It is an accepted paradigm that long-term expression of TGFβ1 promotes a more malignant phenotype, and this is certainly born out by in vitro studies of TGFβ1-treated SCC cells and elevated expression of TGFβ1 in mouse and human cancers where pathway inactivation occurs." (PMID 23326666, 2012). "Here, we demonstrate that transcription factor glioma-associated oncogene 1 (GLI1) modulates EMT through direct up-regulation of SNAI1 and serves as a downstream effector of the transforming growth factor-β1 (TGFβ1) pathway, a well-known regulator of EMT in cancer cells." (PMID 23185371, 2012). "The most clearcut evidence for importance of non-Smad signaling by TGFβ receptors in a cancer phenotype comes from analysis of TGFβ1 mediated EMT." (PMID 23326666, 2012). "It is also important to note that the identification of the TGFβ1-CRP interaction was only captured by AP-MS in the HCT116 cells, but not pulled down in the HEK293T cell line, suggesting that this interaction may be either cell type- or cancer-specific." (PMID 41614767, 2025). "Since TGFβ1 and Twist1 initiate EMT at the top or bottom of the signaling cascade, respectively, these two models can be utilized simultaneously to study at which stage a given gene interferes with EMT, enriching our understanding of cancer metastasis mechanisms." (PMID 39648980, 2024).
cancer (continued). "To validate the differential distribution of myeloid cell subtypes in other cancer types, we classified subtypes of myeloid cells according to the clustering of sub-spot GEPs in HCC tissues, including monocytes, TGFB1+ macrophages (Macro-TGFB1), Macro-SPP1, and MACRO+ macrophages (Macro-MARCO)." (PMID 36806082, 2023). "Indeed, both TGFβ1 and IL6 have been shown to promote EMT and cancer cells metastatic potential." (PMID 36936987, 2023). "In the present study MATH was lower when TGFβ1 and TGFβ3 were higher, while higher levels of TGFβ promoted the formation of an immunosuppressive microenvironment and facilitated the progression of EMT, conditions that favored the evolutionary development of cancer cells." (PMID 36119489, 2022). "In addition, significant enrichment of immunosuppressive cytokines TGFB1 and IL10 have been found in the Epithelial-mesenchymal transition-high group of almost all cancer types, forming an immunosuppressive microenvironment and leading to decreased infiltration of CD8+ T cells." (PMID 36703779, 2022). "Unlike VEGF-A, the role of TGFβ1, a multi-functional cytokine in angiogenesis, however, is less well defined in normal cells and is believed to act as an indirect angiogenic agent, at least in some cancer cells." (PMID 35409127, 2022). "TGFB1 secretion is abolished in fibroblasts and macrophages where key autophagy regulators such as ATG5 and ATG7 are ablated, hinting that targeting TGFB1 release by SA may be beneficial in cancer." (PMID 36601581, 2022). "The down-regulation of transforming growth factor-beta 1 (TGF-β1), vascular endothelial growth factor (VEGF), and MMP-2/9 of MCF-7 cells by HT treatment played an important role in the effect of suppressing invasion ability and apoptosis of residual cancer cells." (PMID 35453310, 2022). "Additionally, in TGFβ1-induced fibrotic models, suppression of FAO and enhancement of glycolysis are observed, highlighting that a shift in bioenergetics, similar to the Warburg effect characteristic of cancer cells, is ongoing during fibrogenesis." (PMID 32210969, 2020). "Moreover, TGFβ promotes Smad-independent signaling thereby activating PI3K/Akt-MAPK or mTOR1 signaling, TGFB1 enhances epithelial plasticity which is likely to progress to EMT in carcinomas." (PMID 32154177, 2020). "The immunosuppressive cytokine TGFβ1 impairs NK cells cytotoxicity by promoting the downregulation of NK cells activating receptors including NKp30 and NKG2D and high serum levels of TGFβ1 have been identified in cancer patients, including in HPV-related malignancies." (PMID 31337018, 2019). "Moreover, TGFβ1 was able to enhance the mRNA expression of Oct4, Nanog and Sox2 and drastically increased anchorage-independent colony formation in TGFβ1–sensitive NSCLC cells, suggesting the acquisition of cancer stem-like properties." (PMID 29995950, 2018). "Among various factors, PDAC cells secrete Transforming growth factor beta-1 (TGF-β1), Fibroblast growth factor-2 (FGF2), sonic hedgehog (SHH) and platelet-derived growth factor (PDGF) that drive fibroblast proliferation and ECM deposition, which in turn, profoundly affect the cancer cell behavior." (PMID 30108679, 2018). "In addition, TGFβ signalling promotes growth, migration, and invasiveness in both human and canine OSA cell lines, and TGFβ1 induces de-differentiation of OSA cells into self-renewing cancer stem cells." (PMID 30477496, 2018). "As TGFβ1 was negative in all carcinomas, downstream genes such as Slug and Smads’ were negative, too, and β-Catenin was regularly located at the cell membranes, ruling out any role for the canonical SARI-GSK3-βCatenin and Wnt-Frizzeld pathways to play in bulk migration." (PMID 29976164, 2018). "Thus, suppressing TGFβ1 expression could target multiple radiation responsive signaling cascade in NPC cells and mediate the sensitivity of cancer cells to radiation treatment." (PMID 28423621, 2017).
cancer (continued). "In the present study, we analysed the expression and regulation of Dies1 in a TGFβ1-induced EMT model, epithelial cancer cell line models and cancer samples, aiming at disclosing a role for this molecule in epithelial carcinogenesis, and the mechanisms that may control its expression and signalling." (PMID 27721458, 2016). "Exosomes from other cancer types may also impart similar effects on driving a myofibroblast-like differentiation process, and MSC of adipose or cord-blood origin have been reported to be responsive to exosomally delivered TGFβ1." (PMID 25596732, 2015). "We chose ERK, TGFB1, TGFB2, SIRT1, IL-6, PI3K, and WHSC1 (which were controlled by several genes) and three other genes AR, BCL-XL, and CCND1 that could mark the deterioration of the cancer, for testing." (PMID 26603105, 2015). "In view of the interactions between S100 proteins and TGFβ1, and the fact that TGFβ1 is a well known inducer of EMT, a relevant biological phenomenon in morphogenesis and in cancer initiation and progression, we ascertained whether the observed molecular interactions also occur in this process." (PMID 24670043, 2014). "Furthermore, expression of TGFβ1 in carcinoma tissue did not correlate with overexpression or underexpression (P=0.954)." (PMID 23251252, 2013). "Moreover, calycosin inhibited the proliferation, invasion, and migration of cancer cells through decreasing MMP‐2, MMP‐9, and CD147 levels through downregulating BATF (basic leucine zipper ATF‐like transcription factor) expression and TGFβ1 (transforming growth factor 1) expression." (PMID 38230908, 2024). "Furthermore, we observed that plastic EpCAMhigh and EpCAMlow cancer cells did not induce the expression of Tgfb1 and Tgfb2 compared with full epithelial cancer cells, ruling out autocrine activation of the TGFβ pathway in epithelial plastic cancer cells to acquire the mesenchymal state." (PMID 39075581, 2024). "Additionally, FJX1 expression was significantly and positively correlated with immunosuppressive genes (TGFB1 and IL-10), chemokines (CCR1 and CCR5), chemokines receptors (CCL2 and CXCL5), and immunosuppressive pathway-related genes (TFGB1 and WNT1), in most TCGA cancers." (PMID 37324001, 2023). "Higher relative transcript levels of the TGFB1 gene were found in cancer cases where blood vessels were not affected by neoplastic cells, which may indicate that the studied gene plays a role in preventing the formation of secondary neoplastic lesions in distant organs." (PMID 35798776, 2022). "In addition, NSC765598 displayed favorable properties as a drug lead compound and thus could be considered a novel small molecule with potential for multi-target inhibition of EGFR/iNOS/mTOR/TGFB1/FGFR/MAP2K1 and could serve as a lead compound for developing new therapeutics for cancer treatment." (PMID 33842373, 2021). "It is tempting to speculate that a finely tuned balance of the opposing actions of aTGFβ and exogenous TGFβ1 does not only control invasion and proliferation, but by inducing a partial/hybrid EMT also generates cancer stem cells and promotes resistance to anti-cancer drugs." (PMID 33802809, 2021). "To check whether the ABCC4 expression upregulation is related to the TGFβ signaling pathway in CRC, we analyzed GSE18105 datasets—which represent the statistically most significant differences in EMT markers between normal and cancer cells—for the expression of TGFβ1/2 and their receptors." (PMID 33261018, 2020). "Besides TGFβ1 and chemo-attractants, activated platelets also secrete autotaxin (ATX); an enzyme with phospholipase D activity that generates LPA from lysophosphatidylcholine and contributes to cancer progression by promoting cancer proliferation, angiogenesis and metastasis." (PMID 28737696, 2017).